IL1B (interleukin 1 beta)
Diseases named in the same sentence as IL1B in open-access papers (continued):
Sharing a sentence is not in itself a finding about the gene and the disease.
depression (continued). "These evidences indicate that IL-1β is not only involved in the occurrence of epilepsy, but also promotes the occurrence of depression in patients with epilepsy." (PMID 32528321, 2020). "IL-1β and IL-6 are secreted by reactive astrocytes and can induce inflammation, and they were proven to be key factors in inducing depression." (PMID 32321532, 2020). "Herein, we investigated the effect of Lactobacillus gasseri NK109, which suppressed IL-1β expression in activated macrophages, on Escherichia coli K1-induced cognitive impairment and depression in mice." (PMID 33182607, 2020). "An increase in IL-1β in depression (M1 activation) is accompanied by an increase in soluble IL-1 receptor antagonist (sIL-1RA) (reflex inhibition)." (PMID 33255237, 2020). "Previous studies have also shown that IL-1β is known to be consistently increased in major depression after psychosocial stress." (PMID 31991875, 2020). "An animal study showed that long-term zeaxanthin treatment decreases the levels of IL-6, IL-1β, and TNF-α and ameliorates diabetes-associated anxiety and depression in diabetic rats." (PMID 31215856, 2020). "The serum levels of IL-1β and homoeostatic model assessment-insulin resistance increase in patients with depression, and neuroinflammation and insulin resistance induced by metabolic imbalance can induce depressive disorder." (PMID 32166013, 2020). "The interleukin-1 beta (IL-1β) and IL-18 levels are increased in the peripheral blood monocytes of patients with major depression due to the activation of NLRP3 inflammasome." (PMID 32328132, 2020). "Conversely, we observed a positive trend for greater IL-1β expression predicting higher anxiety and depression symptoms severity." (PMID 32272662, 2020). "Excessive activation of P2RX7 and NLRP3 leads to increased inflammatory cytokine secretion, such as IL-1β in depression and diabetes." (PMID 32842536, 2020). "Even some polymorphisms of pro-inflammatory cytokine genes, including IL-1β, TNF, and CRP, appeared to be linked with depression and treatment response." (PMID 32517269, 2020). "Clinical depression is accompanied by increased pro-inflammatory cytokine interleukin (IL), such as IL-1β and IL-6." (PMID 33134190, 2020). "First, we found that the baseline levels of IL-10, IL-12p70, IL-13, IL-17A, IL-1β, IL-2, IL-23, IL-5, IL-6, IL-7, and MIP-1β were associated with depression symptoms." (PMID 32699226, 2020). "Based on the univariate analysis of the GLM, we found significant differences in the years of education, cytokines (IL-1β, IL-2, IL-6, IL-12p70, IL-17A, IFNγ, TNFα, IL-10, and IL-13), and depression severity (indicated by the PHQ) among the groups." (PMID 32703187, 2020). "STAT3 is one of the transcription factors regulating the production of the cytokine IL-6, IL-10, TNF-α, and IL-1β, which have been shown to be involved in depression." (PMID 32655424, 2020). "A previous study found that mitogen-stimulated lymphocytes increase IL-1β production in patients with depressive disorders and that a correlation exists between the production of IL-1β and the severity of depressive symptoms." (PMID 31215856, 2020). "Patients diagnosed with MDD and treated with approved medicines for depression presented lower serum levels of IL-1β than before the treatment." (PMID 32848904, 2020). "The reserpine-induced rat depression model significantly elevated the expression levels of IL-1β, IL-6, and TNF-α in the serum, liver and hippocampus of rats compared with the control group (P < 0.01 or P < 0.05)." (PMID 32009949, 2019). "In depressed patients who also suffer from coronary artery disease, statin treatment can downregulate IL-1β expression and function as an anti-inflammation therapy of depression." (PMID 31312123, 2019). "In a chronic mild stress (CMS) model of depression, higher concentrations of IL-1β and IL-6 in the brain and IL-6 and TNF-α in serum were shown." (PMID 30610610, 2019).
depression (continued). "Symptoms of depression are often caused by pro-inflammatory cytokines, mainly due to tumor necrosis factor α (TNF-α), interleukin 1 beta (IL-1β), and interleukin 6 (IL-6)." (PMID 31771312, 2019). "LPS is an effective and potent inducer of inflammatory cytokines (eg, TNF‐α; IL‐1β; IL‐6) that can acutely activate the innate immune system in the peripheral or central nervous system to induce depression‐like behaviours." (PMID 31599060, 2019). "Studies show that the NLRP3 inflammasome in blood cells of patients with MDD was activated, and the increased serum levels of IL-1β and IL-18 were positively correlated with Beck Depression Inventory (BDI) scores." (PMID 31814820, 2019). "Chronic stress, a precipitant of depression, exacerbates age-related increases in inflammatory responses and increases circulating IL-1β and IL-6 and cognitive impairment in elderly patients." (PMID 31383842, 2019). "Other recent meta-analyses revealed evidence of increased CSF levels of IL-1β in schizophrenia and bipolar disorders and increased levels of IL-6 and IL-8 in schizophrenia and depression." (PMID 30116031, 2019). "Associations have been shown between depression and serum levels of CRP, IL-1β, IL-1RA, and MCP-1 in type 2 diabetes patients, with all serum levels being significantly higher in those who are depressed." (PMID 31379879, 2019). "It was found that GTS treatment can alleviate depression‐like behaviour impairments and decrease mRNA levels of IL‐1b, IL‐6, TNF‐a and IDO in the hippocampus." (PMID 31599060, 2019). "Another independent study in major depression also showed that LPS-induced monocytes from patients with depression secreted lower levels of IL-1β, IL-6, and TNFα than those from the control group." (PMID 31152269, 2019). "Recent reports have verified that there are increases in proinflammatory cytokine IL-1β in both younger and elderly adults with major depression." (PMID 31049023, 2019). "Increases in serum pro- and anti-inflammatory cytokines have been observed in patients with depression, such as IL-1β, IL-6, and TNF-α, and IL-10, respectively." (PMID 30678337, 2019). "The main findings of this study indicate a functional network in which several IL-1β-related molecules in CSF influence fatigue in addition to the clinical factors of depression and pain." (PMID 31101054, 2019). "Many studies have highlighted the significance of IL-1β as a pivotal mediator of stress-related disorders including depression." (PMID 30610610, 2019). "LPS activates the innate immune response, resulting in the secretion of various pro-inflammatory cytokines, including TNF-α, IFN-γ, and IL-1β, and the induction of neuroendocrine and neurochemical changes, leading to depression." (PMID 31141940, 2019). "It indicated that serum levels of IL-1β and IL-6 significantly increased in GC patients with depression." (PMID 31396300, 2019). "In depression, high levels of glucocorticoids can co-exist with high levels of pro-inflammatory cytokines such as interleukin (IL)-1β, IL-6, and tumour necrosis factor (TNF)-α." (PMID 31316402, 2019). "Meanwhile, some studies indicated that antidepressant treatment significantly decreased the expression of IL-1β levels in depression patients." (PMID 31049023, 2019). "Patients with depression exhibited an upregulation of proinflammatory cytokines, including interleukin-1β (IL-1β), IL-6, and tumor necrosis factor-α (TNF-α)." (PMID 32009949, 2019). "Previous studies have indicated that chronic stress significantly increases hippocampal IL-1β levels, which plays a key role in the development of depression owing to the high density of hippocampal microglia." (PMID 30760978, 2019). "The main findings of this study indicate a functional network in which several IL-1β-related molecules in CSF influence fatigue in addition to the classical clinical factors of depression and pain." (PMID 31101054, 2019).
depression (continued). "Recently, the role of Nucleotide-binding oligomerization domain (NACHT), Leucine-rich repeat (LRR), and Pyrin domation (PYD) domains-containing protein 3 (NLRP3) inflammasome-dependent IL-1β has emerged as a novel contributor to depressive disorders." (PMID 31263417, 2019). "Animal models of depressive disorders have shown an increase in pro-inflammatory markers, such as interleukin-6 (IL-6), interleukin-1β (IL-1β) and tumor necrosis factor alpha (TNF-α)." (PMID 30678337, 2019). "More importantly, the decreases in neuronal apoptosis within the vmPFC and depression-like behaviors induced by CUMS were also ameliorated by the injection of IL-1β-RNAi virus." (PMID 30666189, 2018). "Recent research has also indicated that activation of NLRP3 inflammasome signaling, a pivotal mediator of IL-1β function, contributes to depression." (PMID 29946236, 2018). "We were also interested in IL-1α levels as many papers in depression focused on IL-1β while neglecting IL-1α." (PMID 29103192, 2018). "These backgrounds support the role of IL-1β in the physiopathology of depression and give meaning to the disturbances that we found in this work." (PMID 30662368, 2018). "In a rat model of IFN-γ-induced depression, hippocampal IL-1β expression and reduced neurogenesis in dentate gyrus was induced and administration of IL-1ra blocked these effects together with the depressive behavior." (PMID 29410649, 2018). "Studies showed that certain cytokines such as IL-1β were involved in the pathogeneses of depression." (PMID 29765402, 2018). "Depression is due to the increased production of pro-inflammatory cytokines by microglia activation, and fluoxetine can attenuate LPS-induced production of IL-1β and p-NF-κB expression in microglia." (PMID 30364169, 2018). "In contrast, 14-days of curcumin treatment following AAV-IL-1β virus injection significantly reversed these depression-like behaviors induced by overexpression of IL-1β within the vmPFC (P < 0.01)." (PMID 30666189, 2018). "In this meta-analysis, elderly with depression or Alzheimer’s disease were found to have significantly higher peripheral IL-1β levels before Bonferroni adjustment." (PMID 30104698, 2018). "A previous study has demonstrated that IL-1β is increased in mPFC in chronic stress-treated rats, while decreasing IL-1β in mPFC also decreased anxiety- and depression-like behaviors." (PMID 30208926, 2018). "There is some evidence that IL-1β is an important mediator of stress-induced depressive-like behavior and depression." (PMID 29343269, 2018). "Post hoc analysis showed that the serum IL-1β level in this depression animal model was significantly increased (P < 0.001)." (PMID 30666189, 2018). "Behavioral testing of depression was then performed at 14-days post-infusion of the small interference RNA sequence form of IL-1β in the AAV virus (AAV-IL-1β-RNAi) in vmPFC of stressed rats." (PMID 30666189, 2018). "The results of this experiment demonstrated that curcumin was effective in reducing the apoptotic and depression-like phenotypes induced by IL-1β overexpression within the vmPFC of rats." (PMID 30666189, 2018). "Our results indicate that changes in the levels of cytokines (such as IL-1β, TNF-α, and IL-8) were associated with the degree of depression." (PMID 29856741, 2018). "Previous research also showed increased mitogen-stimulated IL-1β production and lymphocyte IL-1β mRNA levels in major depression." (PMID 29103192, 2018). "Elderly with depression were significantly higher in their peripheral IL-1β levels than control participants (pooled SMD with random-effects model: 0.642, 95% CI: 0.078–1.206, z = 2.232, p = 0.026)." (PMID 30104698, 2018). "In animal models of stress-induced depression, it was shown that IL-1β signaling was critical to the development of depression-like phenotype." (PMID 29449810, 2018).
depression (continued). "Strikingly, systemic IL-1B and TNFα were significantly elevated and positively correlated with patient anxiety and depression scores in a large clinical study on CP/CPPS patients." (PMID 29731970, 2018). "After Bonferroni adjustment, only peripheral levels of IL-1β remained significantly higher in elderly with depression than controls." (PMID 30104698, 2018). "Depression derives from activation of immune-inflammatory pathways, according to that the release of IL-1β and TNF-α triggers off neuroendocrine and neurochemical deterioration." (PMID 30364169, 2018). "In fact, high levels of IL-1β in the hippocampus and prefrontal cortex have been evidenced by some stress-induced depression experiments in rodent models." (PMID 30662368, 2018). "The ensuing issue to address in these investigations involves identifying the downstream molecular targets of IL-1β in mediating vmPFC neuronal apoptosis in depression." (PMID 30666189, 2018). "Depression affects serum cytokines alterations, including interleukin-1β (IL-1β), IL-6, and IL-8 levels, and leads to inflammatory processes." (PMID 30364169, 2018). "The observations in this study extend the findings from the previous study by showing the effectiveness of long-term fluoxetine treatment in attenuating the high IL-1β production in vivo in a rat model of depression." (PMID 29049348, 2017). "Increased expression of pro-inflammatory cytokines IL-1β, IL-6, TNF-α, as well as interferon gamma (IFN-γ), and C-reactive protein (CRP) is repeatedly observed in patients suffering from depression and has been associated with specific symptoms of depression." (PMID 28239408, 2017). "In recent years, proinflammatory cytokine interleukin-1β (IL-1β) was considered to play a critical role in the pathogenesis of depression." (PMID 28486969, 2017). "In a chronic stress-induced depression model, 10 mg/kg ketamine injection showed a rapid antidepressant effect and effectively reduced the protein expression levels of IL-6, IL-1β, and TNF-α." (PMID 28373844, 2017). "Recently, in addition to 511(C/T), a polymorphism in the promoter region of the IL-1β gene at position 31 (T-31C substitution, located in a TATA-box motif of IL-1β) has been investigated in patients with major recurrent depression." (PMID 27555379, 2017). "Correlation analysis revealed that depression severity negatively correlated with IL-12 in males, and positively correlated with IL-1β and tumor necrosis factor (TNF)-α in females." (PMID 28670290, 2017). "Our results demonstrated that IL-1β knock-down in the hippocampus significantly attenuated the memory deficits and anxiety- and depression-like behaviors induced by LPS in mice." (PMID 28931410, 2017). "And EA like fluoxetine had an anti-inflammatory effect by reducing interleukin-1 beta (IL-1β) to restore the imbalance effects on pro- and anti-inflammatory cytokines in depression patients." (PMID 28400844, 2017). "TNF-α, IL-6, and IL-10 also played important roles in depression induced by stress, which caused the increase of proinflammation cytokines, including TNF-α, IL-6, and IL-1β in serum and hippocampus." (PMID 28694833, 2017). "As a consequence, despite of the high level of cortisol, levels of TNF-α, IL-1b and IL-6 increase what is a common characteristic of major depression." (PMID 28738849, 2017). "Collectively, NLRP3 inflammasome activation and subsequent IL-1β generation were involved in the development of depression and T2D separately." (PMID 29084550, 2017). "Although 5-ASA is a known anti-inflammatory agent, neither treatment with SSZ nor 5-ASA/SP prevented tumour-induced increases in serum levels of interleukin-1β (IL-1β) and IL-6, which are indicated in depressive disorders." (PMID 28120908, 2017). "Depressed patients exhibit increased levels of pro-inflammatory cytokines, e.g., IL-1β, whereas administration of these cytokines (including IL-1β) induces depression-like behavior in experimental animals." (PMID 26581375, 2016).
depression (continued). "Patients or animal models of depression show significant increase of proinflammatory cytokine interleukin-1β (IL-1β) and oxidative stress biomarkers in the periphery or central nervous system (CNS)." (PMID 27026206, 2016). "In support of this concept, increased gene expression of NLRP3 and caspase-1 in the mononuclear blood cells and elevated serum levels of IL-1β and IL-18 have been found in patients with major depression." (PMID 26631274, 2016). "It was observed that chronic unpredictable mild stress-exposed rats, a well-documented model of depression, produced increased IL-1β mRNA and protein levels in the prefrontal cortex, which were not reproduced in serum or cerebrospinal fluid (CSF)." (PMID 26733805, 2015). "The purpose of the study was to examine associations of spiritual pain with psychosocial factors (stress, depression, loneliness, religious coping) and salivary biomarkers of stress and inflammation (cortisol, IL-1β) in Meals on Wheels’ clients." (PMID 27417804, 2015). "Consistently, the pivotal proinflammatory cytokines involved in sickness and depression-related behaviors following infection are IL-1β and TNF-α." (PMID 26170871, 2015). "Considering that anhedonia is one of the core symptoms of depression, the effects of IL-1β administration with a sucrose intake test were investigated." (PMID 26417153, 2015). "Inhibiting this pathway pharmacologically or blocking Il1b signalling using receptor knockout mice, normalised sucrose preference, a measure of anhedonia as well as other depression and anxiety related behaviours." (PMID 25879669, 2015). "In other studies, patients with depression showed increased serum levels of IL-1β, IL-6, IL-8, IL-12 and TNF-α, together with a decrease in IL-10 levels, an anti-inflammatory cytokine." (PMID 26733805, 2015). "It was found that participants with CES-D scores indicating depression had concentrations of IL-1β which were 73 % higher compared to those with lower (<16) CES-D scores (p = 0.05)." (PMID 26545369, 2015). "Elevations in proinflammatory cytokines like prostaglandin E2 (PGE2), C-reactive protein (CRP), TNF-α, IL-1β, IL-2, and IL-6 have been reported in major depressive disorder and, at times, have shown a dose-response with severity of depression." (PMID 26550011, 2015). "IL-6, TNFα, IL-1β and their soluble receptors have been found to be upregulated in patients with major depression." (PMID 26793110, 2015). "Plasma concentrations of the proinflammatory cytokines IL-1 and IL-6 are increased in patients with depression and antidepressant medication reduces the concentrations of cytokines such as IL-1β." (PMID 25593715, 2014). "One study found that BD patients during a mood episode (mania or depression) had decreased IL-1β levels in comparison with major depression patients." (PMID 25313338, 2014). "Rodent studies have shown increased production and expression of IL-1β in the brain after LPS-induced systemic inflammation and changes in mood and behavior similar to depression after systemic administration of pro-inflammatory cytokines." (PMID 25339862, 2014). "Serotonin-reuptake inhibitors are known to decrease TNF-α and IL-1β serum levels in patients with major depressive disorders." (PMID 25364907, 2014). "Patients undergoing cytokine therapy often develop symptoms of depression and elevated levels of cytokines (including IL-6 and IL-1β) are found in both blood and CSF from depressed patients." (PMID 25285951, 2014). "Since IL-1β upregulation is part of a patterned response that unfolds after a wide range of insults including infection, trauma, depression and stroke, it would become a noticeable target for the prevention of MCD during pregnancy." (PMID 24950657, 2014). "IL-1β plays a prominent role in neurodegenerative processes and has recently been identified for its role in murine models of depression-like behavior." (PMID 23634700, 2013).